INS (insulin)
Diseases named in the same sentence as INS in open-access papers (continued):
Sharing a sentence is not in itself a finding about the gene and the disease.
Hyperglycemia (continued). "An explanation may relate to both improved insulin sensitivity and glucose effectiveness observed with exercise, or could be ascribed to a blunted insulin secretion during hyperglycemia, GIP stimulation and arginine stimulation after high volumes of exercise." (PMID 37127822, 2023). "The ameliorative effect of EPE on hyperglycemia is a direct result of increased insulin secretion." (PMID 37397470, 2023). "TRPA1 can detect hyperglycemia and transmit several stimuli involved in insulin secretion." (PMID 37631083, 2023). "This could be due to damage of pancreatic B cells leading to reduced insulin production contributing to hyperglycemia and acidosis." (PMID 37448393, 2023). "In pancreatic dysfunction, the release of insulin/glucagon is impaired, leading to hyperglycemia." (PMID 36900540, 2023). "A patient who spent a lot of time in hyperglycemia may remain in the target glucose range steadily after a change in their insulin regime." (PMID 38875568, 2023). "Furthermore, hyperglycemic clamp experiments showed that, while CON littermates fed an HFD were unresponsive to persistent hyperglycemia, βKO mice remained highly responsive to hyperglycemia-induced insulin secretion." (PMID 37188647, 2023). "In a small-size randomized study, stable post-operative critical care patients receiving parenteral nutrition had similar blood glucose levels and hyperglycaemia rates whether they underwent short or long-acting insulin therapy." (PMID 37330419, 2023). "Excessive FFA levels also damage the pancreas to produce insulin to combat hyperglycemia." (PMID 37033655, 2023). "In response to hyperglycemia, DPP4Is boost insulin production while decreasing glucagon secretion." (PMID 37378205, 2023). "In addition, phlorizin treatment has been demonstrated to prevent hyperglycemia by restoring insulin mRNA expression and β-cell differentiation markers." (PMID 37524865, 2023). "Indeed, as post-HIE hyperglycemia is mainly hypo insulinemic, the brain glucose uptake is partially limited by the inability to mobilize insulin-dependent brain glucose transporter (GLUT1)." (PMID 36484862, 2023). "Continuous insulin infusion can be considered for severe or persistent hyperglycemia." (PMID 37253115, 2023). "Therefore, the inhibition of the DPP-IV activity promotes glucose-dependent insulin secretion and attenuates postprandial hyperglycemia." (PMID 37238844, 2023). "In summary, we have fabricated a self‐crosslinkable polymeric mMN patch capable of encapsulating and delivering insulin at hyperglycemia, as well as preserving the native structure/bioactivity of the peptide via the use of biocompatible HA and protein‐friendly crosslinking conditions." (PMID 37718654, 2023). "In addition, post-75-g glucose challenge hyperinsulinemia is associated with the lower SgIo category, indicating hypoglycemia in these subjects is dependent on insulin excess in response to hyperglycemia." (PMID 37367911, 2023). "Moreover, zinc supplementation elevates insulin content in pancreatic β cells, which attenuates fasting hyperglycaemia and hyperinsulinemia in diabetic mice after 4 weeks." (PMID 36985831, 2023). "Such rare instances might represent overlap syndromes of Hirata ́s disease and adult-onset nesidioblastosis, as the insulin–autoantibody syndrome can provoke both episodes of hypoglycemia and hyperglycemia." (PMID 37371827, 2023). "The complications related to steroid use such as hyperglycemia and subsequent insulin use could have shed more light on the onset of mucormycosis in the diabetic population." (PMID 37731437, 2023). "Increasing evidence from cell or animal models suggests that bioactive compounds may have a direct effect on reducing hyperglycemia, amplifying insulin secretion, and blocking the formation of amyloid plaques." (PMID 36902074, 2023). "We speculate that this reduced glycolytic capability may ensue from a reduced GLUT density or HIF-1 activity in the brain from insulin depletion or hyperglycemia." (PMID 37869511, 2023).
Hyperglycemia (continued). "Therefore, the plant's ability to tolerate oral glucose suggests that its leaves can help reduce diabetic complications connected to hyperglycemia having a similar mechanism with standard medication, which is insulin." (PMID 37842332, 2023). "Hyperglycemia is the sequelae of numerous pathophysiological processes resulting from either the pancreatic beta-cells’ inability to secrete enough insulin or their systemic resistance to insulin." (PMID 36830626, 2023). "Since genipin alleviated hyperglycemia, we next assessed whether it could promote insulin sensitivity and reverse glucose dysregulation in obese mice." (PMID 36768454, 2023). "Male and female mice treated with multiple low-dose STZ developed comparable hyperglycaemia (P < 0.001), in conjunction with reduced plasma and pancreatic insulin concentrations (P < 0.01) and impaired glucose tolerance (P < 0.001) when compared to control mice." (PMID 37650517, 2023). "Despite the risk of hypoglycemia without improving hyperglycemia management, insulin was prescribed to almost all patients." (PMID 37531493, 2023). "In addition, treatment with AKBA also reduced fasting hyperglycemia and partially increased circulatory insulin levels in these diabetic rats." (PMID 37049501, 2023). "However, since a significant insulin release is present in both cases, it is difficult to disentangle the effects of hyperglycemia from the effects of insulin." (PMID 37959313, 2023). "More interestingly, a previous study showed that incremental frailty was associated with increased hyperglycemia rather than hypoglycemia in older adults with T2DM who are on insulin therapy." (PMID 37875981, 2023). "Sixty-three (44%) required insulin therapy and 109 (77%) developed hyperglycemia." (PMID 37484782, 2023). "Type 1 diabetes (T1D) is a chronic disease characterized by hyperglycemia due to the loss of β cells and the consequent lack of endogenous insulin secretion." (PMID 37576973, 2023). "In some of these individuals, hyperglycemia was resistant to even large doses of insulin." (PMID 37369025, 2023). "In a subset of patients, a possible worsening of insulin sensitivity and hyperglycaemia in the luteal phase could be observed." (PMID 36836608, 2023). "Consequently, this can lead to inadequate glucose control and delays in recognizing insulin failure, resulting in hyperglycemia, diabetic ketosis, or ketoacidosis." (PMID 38093983, 2023). "Like other viruses, SARS-CoV-2 infections can trigger a stress response that may decrease insulin secretion, activate the release of cortisol and adrenaline, and stimulate excessive gluconeogenesis, leading to temporary hyperglycaemia." (PMID 37511334, 2023). "The increased ratio of insulin to proinsulin, i.e., improved proinsulin processing, observed in islets of O304-treated compared with untreated db/db mice likely reflects the reduction of hyperglycemia and amelioration of β-cell stress in O304-treated mice." (PMID 37626210, 2023). "The inhibition of insulin signaling may also impair the Glut-4 translocation to cell membranes, thus leading to hyperglycemia, through Janus kinase/signal transducers and the activator of transcription (JAK/STAT) pathway." (PMID 38137918, 2023). "At the same time, all other factors traditionally considered as affecting the ectopic expression of insulin gene (hyperglycemia, liver injury, expression of transcription factors PNM, involving of stem/progenitor cells) in T2D compare to T1D is similar or even less." (PMID 38019818, 2023). "Insulin therapy is the first-line medication therapy to control hyperglycemia during pregnancy." (PMID 37960204, 2023). "Furthermore, it has been shown that STZ-induced hyperglycemia promotes skeletal muscle atrophy with increased p65 phosphorylation and impaired insulin signaling." (PMID 37175224, 2023). "GIP also has lipolytic effects in states of hyperglycemia and low insulin concentration levels." (PMID 37510690, 2023).
Hyperglycemia (continued). "Thus, aging is complicated by disorders such as decreased insulin sensitivity, hyperglycemia, hyperlipidemia or civilization diseases such as diabetes, hypertension and cardiovascular diseases." (PMID 37110134, 2023). "Likewise, a study of patients with critical illness and hyperglycemia on mechanical ventilation reports lower insulin requirements and diminished glycemic variability using a DSNF compared to a high-protein control formula." (PMID 36895277, 2023). "Several protein targets identified in this study could assist in reducing hyperglycaemia through insulin sensitization and regulation of glucose homeostasis." (PMID 36982836, 2023). "Importantly, glucocorticoids promote the development of hyperglycemia, namely, by increasing lipolysis, proteolysis, and gluconeogenesis, and reducing insulin-mediated glucose uptake and glycogen synthesis in skeletal muscle." (PMID 38027216, 2023). "Managing this COVID-19-induced hyperglycaemia requires 1.5 to 2.5 times the baseline insulin doses." (PMID 38192935, 2023). "TRPA1 stimulates insulin secretion in diabetic beta cells and improves hyperglycemia." (PMID 37039840, 2023). "In T1DM with absolute insulin deficiency, prolonged fasting without adequate insulin can lead to excessive glycogen depletion and increased gluconeogenesis and ketogenesis, resulting in hyperglycemia and DKA." (PMID 37630716, 2023). "The Pedersen hypothesis states that maternal hyperglycemia leads to fetal hyperinsulinemia due to overstimulation of the fetal pancreatic cells to produce insulin." (PMID 37900684, 2023). "Hence, it is plausible that SPHK upregulation dominated T2D pregnancies and pregnancies associated with fetal macrosomia, i.e., pregnancies characterized by high fetal and/or maternal insulin levels in addition to hyperglycemia." (PMID 36979912, 2023). "By participating in and regulating signaling pathways, quercetin could protect cells from reactive oxygen species (ROS) and improve hyperglycemia by stimulating the production and release of insulin." (PMID 37047182, 2023). "Likewise, prolonged exposure to hyperglycemia and hyperlipidemia of islets induces glucolipotoxicity that blunts insulin secretion and activates β-cell apoptosis." (PMID 37152942, 2023). "He continued to have hyperglycemia, requiring multiple daily injections of insulin." (PMID 37854477, 2023). "Insulin therapy is initiated for persistent hyperglycemia over 180 mg/dl (10 mmol/L)." (PMID 37120562, 2023). "As a result, even individuals who achieve great HbA1c control with basal insulin may need to treat postprandial hyperglycemia later." (PMID 37264625, 2023). "At present, the mechanism by which insulin, C-peptide, hyperglycemia, dyslipidemia, or aging are altering the VEGF/NO balance in glomeruli is unknown." (PMID 37959313, 2023). "Neutral Protamin Hagedorn (NPH) insulin and insulin analogs to treat hyperglycemia are commonly used in the early post-transplant period, however, these require intensive blood glucose monitoring and patients’ adherence to avoid therapy-associated adverse events." (PMID 37600749, 2023). "Isolated postload hyperglycemia demonstrated similar insulin indices to euglycemic women." (PMID 36950879, 2023). "T2D was characterized metabolically as a state involving not only hyperglycemia but paradoxically also one in which fasting circulating insulin levels could be in the normal or even in the distinctly abnormally high range." (PMID 36834496, 2023). "Several studies from animal and human have revealed that volatile anesthetics could impair glucose tolerance and suppress insulin secretion, which ultimately resulted in perioperative hyperglycemia." (PMID 37559041, 2023). "Whey protein is an exceptional source of BCAAs, which are easily and quickly digested, leading to a rapid increase in BCAA leads in the circulation and insulin release, which may improve postprandial hyperglycemia." (PMID 36904293, 2023).
Hyperglycemia (continued). "However, hyperglycemia can be a potential side effect of ghrelin use which will then require close monitoring of blood glucose levels and adjustment of the insulin therapy accordingly." (PMID 36779088, 2023). "Consumption of these products leads to ameliorate regulation of fat and carbohydrate metabolism, improvement of hyperglycemia, a decrease of dyslipidemia, increased sensitivity to insulin, amendment of adipose tissue metabolism, and decrease in oxidative stress." (PMID 37521997, 2023). "Therefore, the inhibition of DPP-IV has been studied as a novel therapeutic approach to decrease glucose production and increase insulin secretion, aiming to prevent postprandial hyperglycemia." (PMID 38068845, 2023). "Moreover, the impairment in the hepatic insulin signaling culminates in gluconeogenesis increases, which contributes to hyperglycemia, and induces hepatic lipid synthesis, exacerbating steatosis and hypertriglyceridemia." (PMID 37456758, 2023). "Moreover, a diet with a low glycemic index and low glycemic load leads to a decrease in the rate of glucose absorption by the body as a result of reduced hyperglycemia and hyper‐insulin, which can lead to a decrease in systemic inflammation." (PMID 37457160, 2023). "Similarly, studies have shown hyperinsulinemia, hyperglycemia, glucose intolerance, and less insulin sensitivity." (PMID 37970433, 2023). "Acute exacerbations of chronic obstructive pulmonary disease (COPD) with severe hyperglycemia may require insulin to lower glucose levels in people with coexisting type 2 diabetes (T2D) and COPD." (PMID 37242426, 2023). "Moreover, hyperglycaemia increased the hypoxic ventilatory response probably triggered by the action of increased circulating insulin on the CB." (PMID 36999224, 2023). "Volatile anesthetics were more likely to cause perioperative hyperglycemia, cortisol increase, and insulin reduction than propofol in non-diabetic patients." (PMID 37559041, 2023). "Thus, the pancreas produces insulin from β cells that are sensitive to high glucose levels and enables glucose to enter cells, reducing hyperglycemia." (PMID 37050725, 2023). "Due to TPN, patient E developed hyperglycemia requiring transient insulin support." (PMID 36983378, 2023). "Only 3 (4.7%) ICUs indicated they prescribe first line SC insulin in mild hyperglycaemias." (PMID 37330419, 2023). "Interestingly, recent work suggests that BAIBA decreased acute insulin release from INS-1832/3 cells when challenged with submaximal hyperglycemia and lower BAIBA levels were correlated with insulin secretory function in humans." (PMID 37362426, 2023). "According to several studies, insulin resistance or a lack of insulin cause hyperglycemia when there is increased enzymatic action." (PMID 36838577, 2023). "Alternatively, hyperglycemia is known to impair gut barrier function, allowing for increased bacterial translocation and significantly shifts the gut microbiota, which is restored following a return to normoglycemia via insulin." (PMID 37233701, 2023). "Insulin levels must accurately meet the metabolic demand to avoid hypoglycemia or hyperglycemia." (PMID 37745252, 2023). "Baicalin supplementation limited hyperglycemia and improved insulin sensitivity." (PMID 38203600, 2023). "According to many types of research, most of them, including dehydrotumulosic acid, polyporenic acid C, pachymic acid, dehydrotrametenolic acid, and dehydroeburicoic acid, could act as an insulin sensitizer in glucose tolerance tests and reduce hyperglycemia." (PMID 37637945, 2023). "DM is a chronic metabolic disorder characterized by persistent hyperglycemia, resulting directly from defective insulin action, inadequate insulin secretion, or both, leading to abnormalities in carbohydrate, lipid, and protein metabolism and an increase in oxidative stress (OS)." (PMID 37765360, 2023).
Hyperglycemia (continued). "Importantly, THADA deficiency protects mice from high-fat high-sucrose diet- and streptozotocin-induced hyperglycemia by restoring insulin secretion and preserving β-cell mass." (PMID 36823211, 2023). "The cornerstone of the treatment of mild or severe hyperglycemia related to ICPis is insulin." (PMID 37108792, 2023). "Taken together, these findings in tissue-specific cells show that hyperglycemia converges on major insulin, lipid, and fibrosis pathways by DNA methylation to regulate the expression of core genes that consist of but are unlikely to be limited to MTOR, RPTOR, IRS2, TXNRD1, LCAT, SMPD3, and COL1A2." (PMID 36633903, 2023). "Fifth, in the presence of normal serum insulin levels, hyperglycemia may result from the reduced sensitivity of peripheral tissues to insulin signaling, such as the reduced uptake of glucose into the liver, skeletal muscle, or fat tissue." (PMID 36834669, 2023). "Hyperglycaemia is common in critically ill patients, but blood glucose and insulin management may differ widely among intensive care units (ICUs)." (PMID 37330419, 2023). "In this study, we found that P. chinense extract (PCP) supplementation resulted in reduced body weight and hyperglycemia, improved pancreatic tissue injury and insulin sensitivity, and decreased inflammatory cytokines expression in spontaneously diabetic db/db mice." (PMID 37689643, 2023). "As expected, the insulin positive staining was distributed all over the pancreatic islets of the control group, and there were few dark stained β-cells randomly located in the islets’ residue of hyperglycemia group." (PMID 37520251, 2023). "Increased serum concentrations of catabolic hormones after trauma, including cortisol, glucagon, and catecholamines, induce hepatic gluconeogenesis and resistance to the peripheral action of insulin, with consequent hyperglycemia, of which the intensity reflects the severity of injuries." (PMID 36899784, 2023). "Impaired insulin signaling and hyperglycemia are diagnosed among patients with NAFLD; therefore, intestinal barrier disruption and intestinal permeability may equally result from these mechanisms." (PMID 36986052, 2023). "Impaired insulin secretion is needed to generate hyperglycaemia and the conversion to T2D." (PMID 37795366, 2023). "Thus, the primary contributory factor of hyperglycemia is a rise in insulin resistance along with the pancreatic cells’ inability to appropriately react to an increase in insulin release." (PMID 38260139, 2023). "Hyperglycemia and FFA can lead to ROS overproduction; Uncontrolled oxidative stress can increase MDA levels, causing insulin resistance and β cell malfunction." (PMID 37849729, 2023). "Interestingly, the enhancement of this activity stimulates insulin secretion, and it can be accompanied by a reduction in the severity of hyperglycemia." (PMID 37298303, 2023). "Willeit explored the potential effects of curcumin on cardiomyocyte hypertrophy, possible mechanisms of nuclear transcription factor signaling in diabetes, hyperglycemia- and insulin-induced cardiomyocyte hypertrophy, and antihypertrophic effects of curcumin in primary culture." (PMID 36873938, 2023). "The drug treatment of hyperglycemia is to correct the impairment of IF and insulin secretion." (PMID 37000070, 2023). "In addition to hyperglycemia, the influence of diabetic cardiomyopathy should also be excluded; and diabetic patients are more often treated with insulin and other hypoglycemic drugs." (PMID 37061678, 2023). "SGLT2−/− mice with a db/db genetic background exhibited a dramatic improvement in hyperglycemia and plasma insulin levels as well as preserved pancreatic beta cell function, indicating the benefit of SGLT2 mutant mice as a means of demonstrating the efficacy of SGLT2 inhibition." (PMID 37047250, 2023). "Hyperglycaemia results fromalterations in either insulin synthesis or insulin action or receptor." (PMID 37928492, 2023).